SPATS2L (spermatogenesis associated serine rich 2 like)
Synonyms: SGNP; DNAPTP6
Tractability: PROTAC: ubiquitination databases record sites on it; its protein half-life has been measured.
Gene: Protein-coding gene on chromosome 2 (200,305,881 to 200,482,264, forward strand). Ensembl gene ENSG00000196141.
Subcellular location: Cytoplasm; Nucleus, nucleolus
Subcellular location (Human Protein Atlas): Cytosol; Nucleoli
Gene Ontology:
Molecular function: RNA binding
Cellular component: cytosol; nucleolus; protein-containing complex; cytoplasm
Genetic constraint (gnomAD): Loss-of-function variants: 20 observed, 40.25 expected, observed/expected ratio (o/e) 0.5, 90% interval 0.35 to 0.72. The upper end of that interval is the gene's LOEUF score, 0.72, which puts it in group 2 of 6, group 1 being the genes least tolerant of losing a copy. Missense variants: 547 observed, 621.33 expected, observed/expected ratio (o/e) 0.88, 90% interval 0.82 to 0.94. Synonymous variants: 230 observed, 242.02 expected, observed/expected ratio (o/e) 0.95, 90% interval 0.85 to 1.06.
Homologues: Orthologues: chimpanzee SPATS2L (100% identical), macaque SPATS2L (99% identical), dog SPATS2L (94% identical), pig SPATS2L (93% identical), rabbit SPATS2L (93% identical), rat Spats2l (90% identical), mouse Spats2l (89% identical), guinea pig SPATS2L (86% identical), tropical clawed frog spats2l (23% identical), Caenorhabditis elegans Y71F9AL.9 (11% identical). Paralogues in human: SPATS2 (38% identical).
Diseases named in the same sentence as SPATS2L in open-access papers:
SPATS2L is named in the same sentence as 31 diseases in open-access papers, as found by Europe PMC text mining. Sharing a sentence is not in itself a finding about the gene and the disease. The quoted sentences say what the papers report.
asthma (5 papers, 2012 to 2024). "Spermatogenesis associated serine rich 2 like (SPATS2L) has been poorly studied in SLE, but we were able to find, based on previous studies, that SPATS2L has an important role in the development of asthma and is closely associated with the prognosis of glioma patients." (PMID 36405750, 2022). "The strongest association of rs295137 located near the SPATS2L gene (β = 0.4707, SE = 0.1323, p = 0.0004) and the rs2395672 in the intron of the CMTR1 gene with a childhood onset asthma (β = 0.4433, SE = 0.129, p = 0.0006) were established." (PMID 39795959, 2024). "SPATS2L has a well-known role in the manifestation of some human disorders such as asthma and hepatocellular carcinoma." (PMID 35629146, 2022).
glioma (3 papers, 2020 to 2022). A benign or malignant brain and spinal cord tumor that arises from glial cells (astrocytes, oligodendrocytes, ependymal cells). "Also, the prognostic effects of SPATS2L in glioma and the associations between SPATS2L and EGFR and CDKN2A alterations are unknown." (PMID 33959491, 2021). "We found that, compared with grade II–III glioma (LGG), the expression levels of SPATS2L were higher in GBM patients in the GSE4412, GSE16011, GSE43378, GSE83294, TCGA, and CGGA datasets." (PMID 33959491, 2021). "Furthermore, we also measured the protein levels of four selected RBPs (GNL1, SPATS2L, RDM1, and FBXO17) in three glioma cell lines, one astrocytoma cell line (SW1088) and two glioblastoma cell lines (U251 and LN229)." (PMID 33634092, 2020).
Hypertension (3 papers, 2022 to 2025). The presence of chronic increased pressure in the systemic arterial system. "Integrative multi‐omics analyses further identified significant genetic correlations between SPATS2L and AF risk factors such as hypertension and diabetes." (PMID 40416952, 2025). "Among these genes, Spermatogenesis-Associated Serine-Rich 2 (SPATS2L) revealed 21 hypertension-associated SNPs, of which 9 SNPs were ≥4 log-p value." (PMID 35629146, 2022). "Two of the recurrent AF genes also code for functions directly or indirectly linked to AF (CASQ2 and GOSR2), and some genes indicate a possible indirect link related to comorbidities, e.g., hypertension or malignancy (PPFIA4, USP34, WIPF1, SPATS2L, CAND2, and AOPEP)." (PMID 38725839, 2024).
acute myeloid leukemia (2 papers, 2023 to 2024). Acute myeloid leukemia (AML) is a group of neoplasms arising from precursor cells committed to the myeloid cell-line differentiation. "Spermatogenesis associated serine rich 2 like (SPATS2L) was highly expressed in homoharringtonine (HHT) resistant acute myeloid leukemia (AML) cell lines." (PMID 36774517, 2023).
astrocytoma (2 papers, 2020 to 2021). "The high expression levels of SPATS2L in the astrocytoma subtype of LGG patients were also observed in the GSE16011 dataset, compared with the oligodendroglioma subtype." (PMID 33959491, 2021). "Compared with the oligoastrocytoma and oligodendroglioma subtypes, the expression levels of SPATS2L were higher in patients with the astrocytoma subtype of LGG in the TCGA datasets." (PMID 33959491, 2021). "The expression levels of SPATS2L were higher in patients with an astrocytoma subtype of LGG." (PMID 33959491, 2021).
atrial fibrillation (2 papers, 2022). A disorder characterized by an electrocardiographic finding of a supraventricular arrhythmia characterized by the replacement of consistent P waves by rapid oscillations or fibrillatory waves that vary in size, shape and timing and are accompanied by an irregular ventricular response. "Recently, some reports have defined a clear link between SPATS2L and atrial fibrillation, which is an abnormal and sometimes rapid heart rate that occurs when the two upper chambers of the heart have unstable electrical signals." (PMID 35629146, 2022).
diabetes (2 papers, 2020 to 2025). "Thus, SPATS2L may serve as candidate gene to be further validated and a potential biomarker for diabetes." (PMID 32682390, 2020).
liver cancer (2 papers, 2022 to 2024). An epithelial or non-epithelial malignant neoplasm that arises from the liver. "An upregulated expression of SPATS2L, a cytoplasmic RNA-binding protein linked to tumorigenicity in several cancers, has been associated with poor prognosis in esophageal squamous cell carcinoma and liver cancer." (PMID 39309198, 2024). "miR-1269a can down-regulate the expression of SPATS2L and LRP6, thereby inhibiting the proliferation of liver cancer cells; while miR-1269a rs73239138 can inhibit the down-regulation of SPATS2L and LRP6 by miR-1269a to promote the occurrence and development of cancer." (PMID 35252180, 2022).
schizophrenia (2 papers, 2020 to 2022). A major psychotic disorder characterized by abnormalities in the perception or expression of reality. "Polymorphisms of SPATS2L have been linked to hippocampal volume, intelligence, and schizophrenia, which makes it a promising candidate gene to have an influence on FP behavior." (PMID 33004014, 2020). "SPATS2L has been associated with schizophrenia in numerous studies." (PMID 33004014, 2020). "Furthermore, in previous studies, we identified putative enhancer RNAs that target schizophrenia-associated genes as well as numerous genetic variants in genes that have been previously linked to schizophrenia, namely GABRB2, SPATS2L, ZEB2, and KCHN8." (PMID 34954808, 2022). "Among them SPATS2L, ZEB2, and KCHN8, all of which have been identified in schizophrenia studies." (PMID 33004014, 2020).
acute monocytic leukemia (1 paper, 2023). Acute monoblastic leukemia (AML-M5), is one of the most common subtypes of acute myeloid leukemia (AML) that is either comprised of more than 80% of monoblasts (AML-M5a) or 30-80% monoblasts with (pro)monocytic differentiation (AML-M5b). "Higher SPATS2L expression was observed in AML patients with the M5 type (acute monocytic leukemia) than those with the other types in TCGA and our cohorts." (PMID 36774517, 2023).
COVID-19 (1 paper, 2024). A disease caused by infection with severe acute respiratory syndrome coronavirus 2. "Several IFN-related genes, such as SPATS2L, OAS2, ISG15, ZBP1, and IFI44L, exhibited similar patterns of upregulation across both dengue and COVID-19 datasets, while others, such as AIM2 and RTP4, showed distinct regulation." (PMID 38444851, 2024).
Head–neck squamous cell carcinoma (1 paper, 2023). "High SPATS2L (HR = 1.32, p = 0.041) and CBX6 (HR = 0.43, p = 0.000033) mRNA expression was significantly correlated with short OS in head–neck squamous cell carcinoma patients." (PMID 36597889, 2023).
laryngeal squamous cell carcinoma (1 paper, 2022). A squamous cell carcinoma that arises from the larynx. "HOXA11-AS can also act as ceRNA to regulate miR-518a/SPATS2L expression and promote cisplatin resistance in laryngeal squamous cell carcinoma." (PMID 35706412, 2022).
lymphoblastic leukemia (1 paper, 2013). "Finally, a recent genome-wide association study (GWAS) data on risk loci for lymphoblastic leukemia has shown a significant association of a Single Nucleotide Polymorphism in the SPATS2L locus." (PMID 24267790, 2013).
ovarian carcinoma (1 paper, 2024). A malignant neoplasm originating from the surface ovarian epithelium. "Upon correlating our study's findings with the existing literature, we observed that silencing FGF8 in ovarian cancer cells resulted in the downregulation of several proteins associated with cancer progression, including SLC7A5, FHL2, SPATS2L, and DAD1." (PMID 39309198, 2024).
psoriasis (1 paper, 2013). An autoimmune condition characterized by red, well-delineated plaques with silvery scales that are usually on the extensor surfaces and scalp. "Therefore, it is tempting to speculate that SPATS2L is involved in a common genetic pathway associated with psoriasis and lymphoproliferative-type of disorders." (PMID 24267790, 2013). "This study has identified two new genes, SPATS2L and KLF6, strongly associated with T cell activation in psoriasis." (PMID 24267790, 2013). "Using weighted correlation analysis we identified SPATS2L and KLF6 coexpression networks, which were also significantly associated with psoriasis (p-value < 0.05)." (PMID 24267790, 2013). "After technical validation, we used an independent sample of patients and controls recruited from the same University Hospitals to validate the association of SPATS2L, KLF6 and SP140 genes with the activation of T cells in psoriasis." (PMID 24267790, 2013). "Therefore, the overexpression of SPATS2L in activated T cells from psoriasis patients could be contributing to an earlier activation of these lymphocytes compared to healthy controls." (PMID 24267790, 2013). "Using an independent cohort of 8 patients and 8 healthy controls we validated the overexpression of SPATS2L (p-value =0.0009) and KLF6 (p-value =0.0012) genes in activated T cells from psoriasis patients." (PMID 24267790, 2013). "We have identified SPATS2L and KLF6 as the two genes most significantly overexpressed in activated T cells from psoriasis patients and we have validated this overexpression in an independent case-control cohort." (PMID 24267790, 2013). "Using in vitro activated T cells from 8 patients and 8 controls we significantly validated the overexpression of SPATS2L (FC = 1.58, p-value = 0.0014) and KLF6 (FC = 1.23, p-value = 0.024) genes in psoriasis." (PMID 24267790, 2013).
Sepsis (1 paper, 2019). Sepsis is defined as life-threatening organ dysfunction caused by a dysregulated host response to infection. "We identified 687 differentially expressed genes between ARDS and ARDS-HSCT (adjusted p-value < 0.01), including IFI44L, OAS3, LY6E, and SPATS2L that had increased expression in ARDS vs. ARDS-HSCT; these genes were not differentially expressed in sepsis vs sepsis-HSCT." (PMID 30665420, 2019).
cancer (3 papers, 2022 to 2024). A tumor composed of atypical neoplastic, often pleomorphic cells that invade other tissues. "Given that SPATS2L is little studied in cancer, including AML, we sought to identify its protein localization and expression characteristics in AML cells and patients." (PMID 36774517, 2023).
tumor (3 papers, 2018 to 2023). "The results showed SPAST2L control group had a higher tumor burden and shorter survival than the SPATS2L KD groups." (PMID 36774517, 2023). "This polymorphism also was found to reduce the tumor suppressor effect of miR-1269a possibly by attenuating the expression level of miR-1269a in HCC cells and overexpression of target genes SPATS2L and LRP6, and promoted the susceptibility to HCC." (PMID 29467929, 2018). "Altogether, these animal experiments suggest that SPATS2L inhibition could suppress tumor growth and prolong the survival of AML mice." (PMID 36774517, 2023).
psychiatric disorder (1 paper, 2020). A disorder characterized by behavioral and/or psychological abnormalities, often accompanied by physical symptoms. "Among them SPATS2L, ZEB2, KCHN8, and MRPL13 which have been previously connected to psychiatric disorders with the latter two being responsive to nicotine treatment." (PMID 33004014, 2020).
SPATS2L also shares sentences with these, for which no sentence is quoted: hepatocellular carcinoma (2 papers); cerebral malaria (1); chronic lymphocytic leukemia (1); dengue (1); esophageal squamous cell carcinoma (1); glioblastoma (1); infection (1); leukemia (1); oligoastrocytoma (1); oligodendroglioma (1); T-cell acute lymphoblastic leukemia (1).